NHERF4 (NHERF family PDZ scaffold protein 4)
Description:
Acts as a regulatory protein that associates with GUCY2C and negatively modulates its heat-stable enterotoxin-mediated activation. Stimulates SLC9A3 activity in the presence of elevated calcium ions.
Synonyms: NaPi-Cap2; IKEPP; PDZD3; PDZK2; FLJ22756
Tractability: Antibody: UniProt places it where antibodies can reach, with high confidence; its Gene Ontology location is reachable by antibodies, with high confidence.
Gene: Protein-coding gene on chromosome 11 (119,185,457 to 119,190,223, forward strand). Ensembl gene ENSG00000172367.
Subcellular location: Cell membrane; Cytoplasm
Pathways (Reactome):
Disease: Intestinal infectious diseases
Gene Ontology:
Molecular function: guanylate cyclase inhibitor activity; protein binding; ubiquitin-specific protease binding; ion channel inhibitor activity; protein-membrane adaptor activity; signaling receptor binding
Biological process: monoatomic ion transport; protein localization to plasma membrane; receptor guanylyl cyclase signaling pathway; response to toxic substance; water transport
Cellular component: apical junction complex; apical part of cell; brush border; cytoplasm; plasma membrane; apical plasma membrane; cytosol; membrane
Genetic constraint (gnomAD): Loss-of-function variants: 51 observed, 51.41 expected, observed/expected ratio (o/e) 0.99, 90% interval 0.79 to 1.25. The upper end of that interval is the gene's LOEUF score, 1.25, which puts it in group 5 of 6, group 1 being the genes least tolerant of losing a copy. Missense variants: 612 observed, 639.15 expected, observed/expected ratio (o/e) 0.96, 90% interval 0.89 to 1.02. Synonymous variants: 259 observed, 262.74 expected, observed/expected ratio (o/e) 0.99, 90% interval 0.89 to 1.09.
Homologues: Orthologues: macaque NHERF4 (97% identical), chimpanzee NHERF4 (94% identical), pig NHERF4 (83% identical), rabbit NHERF4 (82% identical), mouse Nherf4 (81% identical), dog NHERF4 (81% identical), guinea pig NHERF4 (80% identical), rat Nherf4 (80% identical), tropical clawed frog nherf4 (35% identical), zebrafish nherf4a (35% identical), zebrafish nherf4b (33% identical), Caenorhabditis elegans nrfl-1 (18% identical). Paralogues in human: PDZK1 (30% identical), NHERF2 (21% identical), NHERF1 (20% identical).
Diseases named in the same sentence as NHERF4 in open-access papers:
NHERF4 is named in the same sentence as 4 diseases in open-access papers, as found by Europe PMC text mining. Sharing a sentence is not in itself a finding about the gene and the disease. The quoted sentences say what the papers report.
Hypercalciuria (1 paper, 2016). "Interestingly, NHERF4 is a known regulator of the Ca2+ channel TRPV6 that mediates the entry of dietary Ca2+ from the intestinal lumen into the enterocyte in the course of transepithelial transcellular Ca2+ absorption, which is nicely in line with the absorptive hypercalciuria we report." (PMID 26756164, 2016).
NHERF4 also shares sentences with these, for which no sentence is quoted: bacterial infection (1 paper); cancer (1); tumor (1).